PPARA (peroxisome proliferator activated receptor alpha)
Diseases named in the same sentence as PPARA in open-access papers (continued):
Sharing a sentence is not in itself a finding about the gene and the disease.
dyslipidemia (439 papers, 2005 to 2026). "PPARA L162V polymorphism, associated with reduced gene activity, has important effects in dyslipidemia." (PMID 40806580, 2025). "A positive correlation has been found between the PPARA (gene encoding PPAR-α) DNA methylation level and the metabolic syndrome index, triglyceride concentrations and HOMA-IR (HOmeostatic Model Assessment for Insulin Resistance)." (PMID 36613595, 2022). "In contrast to these findings, a recent study reported a positive association between increased PPARα methylation and metabolic syndrome, higher triglyceride levels and homeostasis model assessment of insulin resistance (HOMA-IR)." (PMID 36992770, 2022). "Along with the regulation of lipid and glucose metabolism, PPARα is an attractive candidate gene for the risk of metabolic syndrome and T2D." (PMID 36618347, 2022). "Search terms included PPARα polymorphisms, metabolic syndrome, diabetes, non-alcoholic fatty liver disease (NAFLD), and atherosclerosis." (PMID 31489930, 2019). "Naringin, in addition to its potent antioxidant nature, affects AMPK-, CPT1–, and PPARa– mediated fat utilization, and also preserves mitochondrial function in the treatment of diabetes, metabolic syndrome, and associated complications." (PMID 29593575, 2018). "Once activated, PPARα regulates genes that encode for mitochondrial and peroxisomal β-oxidation, which reduces dyslipidemia." (PMID 28348577, 2017). "Single nucleotide polymorphisms (SNPs) in PPARα, that is, L162V, V227A, and intron 7G>C, are associated with metabolic features, such as dyslipidemia, CVD, and type II diabetes." (PMID 28042289, 2016). "Both in vivo and in vitro studies have demonstrated that PPARα regulates the expression of some genes involved in lipid metabolism and plays a central role in the control of dyslipidemia associated with the metabolic syndrome." (PMID 25923694, 2015). "Upon high fat diet feeding, PPARα contributes to liver homeostasis by limiting steatosis and improving the atherogenic lipoprotein profile associated with type 2 diabetes and the metabolic syndrome." (PMID 25141153, 2014). "Multivariate logistic regression analysis was performed to identify the associations of the APOE, SCARB1, PPARα genotypes with the prevalence of dyslipidemias in the study population." (PMID 23919842, 2013). "Fenofibrate, an agonist of PPARα, is a useful therapeutic option for patients with dyslipidemias, particularly those associated with diabetes mellitus or coronary heart disease, and metabolic syndrome." (PMID 19592476, 2011). "In vivo and in vitro studies demonstrate that PPARα plays a central role in lipid and lipoprotein metabolism, and thereby decreases dyslipidemia associated with metabolic syndrome." (PMID 20871824, 2010). "The 162Val PPARα SNP is a loss-of-function allele that has been associated with decreased hepatic lipolysis, dyslipidemia and progression of type 2 diabetes." (PMID 20825652, 2010). "Treatment oftype 2 diabetes-associated dyslipidemia with gemfibrozil, an antidyslipidemicagent and PPARα activator, stabilized urinary albuminexcretion rates." (PMID 19277201, 2008). "PPARα/γ dual agonists have also been developed, because type 2 diabetes and metabolic syndrome are often associated with high lipid and glucose level in blood." (PMID 18355413, 2008). "PPARα activators have been used to treat dyslipidemia, causing a reduction in plasma triglycerideand elevation of high-density lipoprotein cholesterol." (PMID 18584037, 2008). "PPARα is a well-established regulator of enzymes involved in lipid metabolism and FA oxidation; thus, its knockout has been consistently associated with impaired β-oxidation and the development of dyslipidemia." (PMID 40863118, 2025). "Saroglitazar’s PPARα activation is mechanistically linked to increased lipid oxidation and enhanced clearance of triglyceride-rich lipoproteins, supporting its role in improving dyslipidemia." (PMID 41583325, 2025).
dyslipidemia (continued). "Besides dyslipidemia, the downregulation of the PPARα gene has also been linked to glomerular matrix expansion, inflammatory cell infiltration, and proteinuria in animal models with diabetic nephropathy." (PMID 39265079, 2024). "Other examples include reduced methylation of the peroxisome proliferator-activated receptor alpha (PPARα) and glucocorticoid receptor (GR) genes; increased expression of these genes is associated with an increased risk of metabolic syndrome and cardiovascular disease." (PMID 39599588, 2024). "The best known synthetic ligands of PPARα are fibrates (e.g., clofibrate, fenofibrate, and bezafibrate), a class of drugs used to reduce the risk of cardiovascular disease in patients with dyslipidemia due to their ability to lower plasma triglyceride levels and elevate HDL cholesterol." (PMID 33799988, 2021). "We hypothesize that PPARα activation by mono-palmitoyl-glycerols may underlie part of the beneficial metabolic effects induced by A. muciniphila in human metabolic syndrome." (PMID 33477821, 2021). "PPARα is widely implicated in the upregulation of mitochondrial uptake and oxidation of fatty-acids, and downregulation of OxS, inflammation, insulin resistance, metabolic syndrome and fatty liver." (PMID 33007928, 2020). "PPARα may be implicated in metabolic disease models such as metabolic syndrome, dyslipidemia and diabetes." (PMID 30872768, 2019). "The activation of PPARα, particularly by drugs or nutraceuticals, exerts a central role in lipid and lipoprotein metabolism and may reduce the dyslipidemia associated with the MetS." (PMID 31489930, 2019). "Here we wanted to test the concept that a combined PPARα/γ agonist could improve metabolic flexibility in a widely used animal model of insulin resistance and dyslipidemia associated with obesity, the fa/fa Zucker rat." (PMID 24285952, 2013). "The associations of the SCARB1 and PPARα genotypes with dyslipidemia were found only in men." (PMID 23919842, 2013). "Although the therapeutic potential of PPARβ/δ for metabolic diseases such as insulin resistance, dyslipidemia, and other associated liver pathologies deserves further investigations, agonists of PPARγ and PPARα have been developed as relevant drugs to treat these disorders." (PMID 23024649, 2012). "Beyond nutritional situations, interest in PPARα effects on amino acids metabolism can also be considered in light of the involvement of specific amino acids in physiopathological processes associated with the metabolic syndrome." (PMID 21915176, 2011). "to assess the effect of functional single nucleotide polymorphisms (SNPs) of PPARα and PPARγ2, previously associated with insulin resistance and dyslipidemia, on liver damage in NAFLD, whose progression is influenced by metabolic abnormalities and inherited factors." (PMID 20825652, 2010). "PPARα activators improve the dyslipidemia associated with type 2 diabetes and may be particularly beneficial in lowering risk of CVD in subjects with type 2 diabetes or metabolic syndrome." (PMID 16309557, 2005). "Network pharmacology analysis showed that some popular metabolic targets for the FDA-approved antidiabetic drugs, such as PPARG and PPARA, the targets of pioglitazone, might play a great role in MA activity against insulin resistance and dyslipidemia associated with T2DM." (PMID 36160451, 2022). "Patients with CKD have decreased renal expression of PPARα and frequently suffer from various systemic disorders, including dyslipidemia, hypoglycemia, malnutrition, frailty, and sarcopenia." (PMID 41460648, 2026). "PPARα activation turned out to be a promising therapeutic method for treating dyslipidemia, inflammation, and insulin sensitivity." (PMID 39941353, 2025). "Peroxisome proliferator-activated receptor alpha (PPARα) is a known metabolic regulator of lipid metabolism in the gut and liver and is an attractive therapeutic target for metabolic syndromes and NAFLD." (PMID 40793786, 2025).
dyslipidemia (continued). "Fenofibrate, the peroxisome proliferator-activated receptor alpha (PPARA) agonist used for dyslipidemia, stimulated mitochondrial FA beta-oxidation, restored left ventricular function, and reduced myocarditis and fibrosis in a murine model of chronic CCC." (PMID 40297326, 2025). "PPARα, primarily expressed in the liver, heart, and muscle, promotes fatty acid oxidation and cholesterol metabolism, making it a target for treating dyslipidemia and CVDs." (PMID 40926269, 2025). "Fibrates, like fenofibrate and bezafibrate, have been used for decades to modulate PPARα activity, improving lipid profiles and reducing cardiovascular risks in patients with metabolic syndrome." (PMID 40926269, 2025). "PPARα agonists,including fibrates (e.g., fenofibrate), have been used for decadesto manage dyslipidemia and are well tolerated, with an excellent safetyprofile." (PMID 39879378, 2025). "Consistently, a previous study demonstrated that ursolic acid decreased SREBP-1c, FASN, and ACC1 expression levels via activating PPARα in the liver, alleviating liver lipid accumulation and dyslipidemia in obese rats." (PMID 39942052, 2025). "Previous studies have demonstrated that long-term dietary intervention with fenofibrate (a PPARα agonist) reduced HFD-induced dyslipidemia and insulin resistance." (PMID 39942052, 2025). "The PPARα agonists fenofibrate and pemafibrate ameliorate dyslipidemia and reduce hepatic stiffness." (PMID 40564141, 2025). "Fibrates, such as fenofibrate and bezafibrate, act as PPARα agonists and have shown promising results in reducing cardiovascular events in patients with metabolic syndrome and diabetic dyslipidemia." (PMID 40926269, 2025). "PPARα agonists primarily target lipid metabolism and are used to treat dyslipidemia and decrease triglyceride levels." (PMID 40943672, 2025). "It was emphasized that PPARα activation can effectively alleviate dyslipidemia and that PPARγ agonists reduce insulin resistance." (PMID 39062500, 2024). "Agonists of PPARα have lipid-lowering action, such as lowering TGs, and they have long been used to treat dyslipidemia." (PMID 39458470, 2024). "PPARα agonists are highly significant in managing dyslipidemia and metabolic syndromes by reducing plasma triglyceride levels." (PMID 39434882, 2024). "In previous studies conducted in our laboratory, we observed that PPARα activation with fenofibrate promotes an increase in the expression of the PI3K/Akt pathway in a model of metabolic syndrome and I/R." (PMID 39518943, 2024). "Patients with metabolic syndrome have been found to have significant hyperlipidemia dependent on a different DNA methylation of PPARα." (PMID 39062500, 2024). "One such candidate is pemafibrate (PEM), a selective peroxisome proliferator-activated receptor-alpha (PPARα) modulator recently approved in Japan in 2018 for dyslipidemia." (PMID 38828415, 2024). "This suggests that DNA methylation, especially PPARA, LPL, SCD and TNF-α, is implicated in metabolism dysregulation and the pathogenesis of metabolic syndrome, involving adipose tissue metabolism dysregulation and the induction of the anti-inflammatory state." (PMID 39595621, 2024). "In this study, we found that the deletion of NCoR1 in intestinal epithelial cells (IECs) mainly activated the nuclear receptor PPARα and attenuated metabolic syndrome by stimulating thermogenesis." (PMID 39807334, 2024). "Previous studies have shown that loss of peroxisome proliferator-activated receptor alpha (PPARα) in the liver results in inflammation and hyperlipidemia in response to HFD, and PPARα agonists are approved for the treatment of dyslipidemia." (PMID 39224121, 2024). "Fenofibrate is a fibrate drug, as a PPARα agonist, it is widely used to lower lipids against dyslipidemia." (PMID 38173037, 2024). "Activation of PPARα not only ameliorates the metabolic syndrome but also exhibits anti-inflammatory effects." (PMID 38790653, 2024).
dyslipidemia (continued). "Pemafibrate, a new member among the selective PPARα modulators, is commonly used in Japan to treat dyslipidemia." (PMID 38613031, 2024). "This suggests that DNA methylation of the nuclear receptors PPARγ and PPARα is correlated with metabolic deregulation, the pathogenesis of metabolic syndrome, and the induction of inflammation." (PMID 39062500, 2024). "We also observed that PPARα activation optimizes cardiac metabolism, improves vasodilation, and preserves cardiac structure during I/R in the heart of rats with metabolic syndrome." (PMID 39518943, 2024). "Downregulation of Gpx1, Pparα, and Sod1 transcripts by HFD exposure and mixed HFD and PM2.5 exposure affects this pathway, increasing the risk of dyslipidemia." (PMID 39766314, 2024). "Some studies have demonstrated the various DNA methylation patterns of PPARA in patients with metabolic syndrome and significant hyperlipidemia." (PMID 39595621, 2024). "Thus, the PPARα-activating nucleoside analogs tenofovir-disoproxil-fumarate may usefully treat atherosclerosis and hepatocarcinogenesis, both of which are associated with dyslipidemia." (PMID 36831317, 2023). "PPARα agonists (fibrates) are used to treat dyslipidemia by decreasing triglyceride and increasing high-density lipoprotein (HDL) levels." (PMID 36768666, 2023). "PPARα agonists, fibrates, were approved for human use several decades ago for the treatment of dyslipidemia." (PMID 37427406, 2023). "FF, one of the PPARα agonists, is a derivative of fibric acid and is commonly applied in the treatment of adults with dyslipidemia, primary hypertriglyceridemia, and hypercholesterolemia." (PMID 38023298, 2023). "Saroglitazar (a PPARα/γ dual agonist) is an anti-metabolic syndrome drug developed locally in India by the company named Zydus Cadila in 2001, which can improve insulin sensitivity, lipid, and glycemic parameters." (PMID 37063264, 2023). "Pemafibrate (K-877) is a novel selective PPARα modulator that improves dyslipidemia, plasma transaminase level, and the pathological condition of NASH in animal trials." (PMID 37063264, 2023). "The Helsinki heart study randomized 4180 men with primary dyslipidemia to the PPARα agonist gemfibrozil or a placebo." (PMID 36768666, 2023). "Given the similarities in their structures, all five PPARα activators clustered together, with WY-14,643 and fenofibrate being more similar to one another compared to the set of compounds designed to treat dyslipidemia (CP-868388, CP-775146, and CP-865520)." (PMID 38133364, 2023). "Pemafibrate used in clinical practice for dyslipidemia was developed as a selective PPARα modulator (SPPARMα)." (PMID 37456852, 2023). "The PPARα and PPARγ agonists, fibrates and thiazolidinediones (TZDs), respectively, are in clinical use for several decades as medications to treat dyslipidemia and hyperglycemia in patients with T2DM." (PMID 37893070, 2023). "LBW mice are more prone to dyslipidemia probably due to downregulated bile acid metabolism-related PPARα/CYP4A14 pathway, resulting in insufficient metabolism of cholesterol to bile acids, which, in turn, leads to elevated blood cholesterol." (PMID 36794015, 2023). "Gemfibrozil is a ligand of peroxisome proliferator-activated receptor α (PPARα) and acts as a fibrate drug for dyslipidemia in humans." (PMID 36835510, 2023). "To exclude potential impacts secondary to systemic dyslipidemia in global PPARα KO, we generated epithelium-specific PPARα conditional KO and transgenic mice for this study." (PMID 36943878, 2023). "Fenofibrate is a fibric acid derivative developed for therapy of patients with hypertriglyceridemia as well as other dyslipidemias via activation of PPARα." (PMID 36172518, 2022). "HMC also significantly stimulated AMPKThr172 and PPARα in the liver, and ameliorated dyslipidemia by inhibiting SREBP-1c and FAS." (PMID 35565920, 2022).
dyslipidemia (continued). "Fenofibrate is a specific agonist of PPARα and is used clinically to reduce lipid levels in patients with dyslipidemia and cardiovascular disease." (PMID 35222033, 2022). "Here, we aimed to study the effects of the novel selective PPARα modulator, pemafibrate, on metabolic parameters in patients with dyslipidemia." (PMID 35203610, 2022). "Prompted by our differential expression profiling pointing to possible PPAR involvement, we treated patient and control fibroblasts with fenofibrate, a widely adopted PPARα agonist for treatment of dyslipidemia." (PMID 35996156, 2022). "In the polar cells, the top associated down-regulated pathways included visceral fat deposits and the metabolic syndrome (P = 0.043) and basic mechanism of action PPARa, PPARb(d) (P = 0.03)." (PMID 35948369, 2022). "These pathways serve to protect the host from dyslipidemia, but presumably they require levels of PPARα protein that exceed what is present during chronic undernutrition." (PMID 35419389, 2022). "PPARα shows protective effects in metabolic syndromes including MAFLD and diabetes, as well as its benefit for cardiovascular health." (PMID 36589809, 2022). "To identify the molecular mechanisms underlying the ability of HMC to improve dyslipidemia, we investigated the expression of AMPK, the lipogenesis-related transcription factors PPARα and SREBP-1c, and the lipogenesis-related enzyme FAS, in the liver." (PMID 35565920, 2022). "The most important class of medications to manage dyslipidemia due to insulin resistance can be PPARα agonists such as fibrates, because PPARα agonists induce a greater reduction of TG and a greater increase of HDL-C." (PMID 35408799, 2022). "On the function of PPARα in metabolic syndrome, PPARα is probably involved in the regulation of CVD." (PMID 36589809, 2022). "Fenofibrate (FBR), an oral medication used to treat dyslipidemia, is a ligand of the peroxisome proliferator-activated receptor α (PPARα), a nuclear receptor that regulates the expression of metabolic genes able to control lipid metabolism and food intake." (PMID 36614161, 2022). "PPARα agonists are used in the treatment of dyslipidemia and are being examined for their ability to ameliorate NAFLD, illustrating the importance of PPARα in lipid metabolism." (PMID 36115532, 2022). "This review summarized the recent findings of PPARα in metabolic syndrome, Alzheimer’s disease, and cardiovascular disease and discussed unsolved questions of the role of PPARα in cancers." (PMID 36589809, 2022). "Fenofibrate, a PPARα agonist, is widely prescribed for the treatment of dyslipidemia, type 2 diabetes, and metabolic syndrome." (PMID 36358696, 2022). "An emerging role in the prothrombotic tendency related to dyslipidemia is the activation of peroxisome proliferator-activated receptor alpha (PPARα) signalling supporting platelet activity." (PMID 36232746, 2022). "Palmitoyl monoacylglycerols 1- and 2-PG were identified as endogenous agonists of PPARα, but not PPARγ; therefore, the beneficial effects of A. mucuniphila in the metabolic syndrome can be attributed to the activation of PPARα." (PMID 36430628, 2022). "Fenofibrate, a selective PPARα activator used to treat dyslipidemia in humans, has been shown to reduce inflammation in rheumatoid arthritis patients." (PMID 35565236, 2022). "Not only are PPARs directly involved in metabolic syndrome and fasting but activation of PPARα has been shown to play a critical role in decreasing apoptosis and inflammation during renal IRI in a mouse model." (PMID 35432296, 2022). "The effect of resveratrol in the presence of quercetin has been studied on PPARα-mediating uncoupling protein regulation in visceral white adipose tissue from metabolic syndrome rats." (PMID 34445672, 2021). "Although PPARα has the function of promoting eNOS synthesis and repairing cell damage, novel PPARα drugs with therapeutic potential for metabolic syndrome and cardiovascular diseases both target the lipid reduction." (PMID 33728018, 2021).